APC (APC regulator of Wnt signaling pathway)
Diseases named in the same sentence as APC in open-access papers (continued):
Sharing a sentence is not in itself a finding about the gene and the disease.
epidermoid cysts (6 papers, 2016 to 2025). "Some reports have shown a higher incidence of epidermoid cysts and a more severe desmoid disease in patients with a mutation between codon 1445 and codon 1580 than in patients with mutations in other regions of the APC gene." (PMID 29368261, 2018). "The combination of multiple polyps in stomach, duodenum, and colon, together with epidermoid cyst, dental abnormalities signifies towards GS, which is further confirmed by APC gene defects." (PMID 33787608, 2021).
renal cell carcinoma (6 papers, 2012 to 2024). "In renal cell carcinoma APC and β-catenin mutations are uncommon events." (PMID 22325146, 2012). "APC Pro1433Leu was also detected in renal cell carcinomas, and these results suggest that the tumor in case 2 arose from an odontogenic epithelium by mutations found in other cancers." (PMID 32113465, 2020). "The cited authors report that VHL, BAP1, FH, and MET are specific genes that increase the risk of developing renal cell cancer, whereas CHEK2, MUTYH, APC, and STK1 are not typically associated with the development of renal tumours." (PMID 39336594, 2024).
schizophrenia (6 papers, 2013 to 2025). A major psychotic disorder characterized by abnormalities in the perception or expression of reality. "APC is a tumor suppressor gene located on 5q21–22, a site reported to also be associated with schizophrenia." (PMID 26436104, 2015). "The APC gene has also been claimed to be associated with susceptibility to schizophrenia, providing an additional line of evidence for the important role that APC protein may have in the etiology of neurodevelopmental disorders." (PMID 32123549, 2020). "This may suggest that increased expression of APC is associated to attenuated Wnt pathway signalling in this animal model of schizophrenia." (PMID 24403877, 2013). "The adenomatous polyposis coli (APC) gene has been associated with FAP (familial adenomatous polyposis), and studies have linked it to schizophrenia." (PMID 26436104, 2015). "A review of literature about the role of APC in schizophrenia as well as implications of genetic counseling on those who suffer with mental illness will be discussed." (PMID 26436104, 2015). "We aim to bring to light the need for future investigations to better understand what role APC has in schizophrenia as well as the implications of genetic counseling on those who suffer with mental illness." (PMID 26436104, 2015). "ZFHX3, RND3, KLF5, ERBB4, EGR1 and APC genes are both schizophrenia candidate genes and tumor suppression genes." (PMID 24564241, 2013). "This study showed a significant increase in both APC mRNA and protein levels in the prefrontal cortex and the ventral tegmental area of mice displaying dizocilpine-induced schizophrenia-related behaviour, compared to controls." (PMID 24403877, 2013). "Interestingly, preliminary findings implicate the APC gene in psychiatric disorders such as schizophrenia and depression." (PMID 32123549, 2020). "Hence, studies examining the role of the APC protein among individuals with other neurodevelopmental conditions that manifest cognitive impairment, such as autism spectrum disorders and schizophrenia are warranted." (PMID 32123549, 2020). "Backing the increased APC-induced Wnt down-regulation hypothesis, another study found an increased APC mRNA expression in leukocytes from patients with schizophrenia, which was independent from antipsychotic treatment." (PMID 24403877, 2013).
ampullary carcinoma (5 papers, 1998 to 2023). "Such a finding was somewhat in contrast with the reportedly low frequency of APC gene mutations in ampullary cancers, located at chromosome 5q21, and suggested that loci different from that of APC might be the target of chromosome 5 allelic losses (LOH) in these tumours." (PMID 9862579, 1998). "The most frequent gene alteration in ampullary cancer was found in APC (23%), followed by CTNNB1 (9%), RNF43 (8%), CDH1 (1.9%), and WNT1 (1.3%)." (PMID 32764696, 2020).
Barrett esophagus (5 papers, 2009 to 2025). Esophageal lesion lined with columnar metaplastic epithelium which is flat or villiform. "Further study on the mucosa of patients at risk for developing Barrett's esophagus, a condition which progresses to adenocarcinoma of esophagus, has shown 88% methylation of APC promoter." (PMID 19149902, 2009).
brain cancer (5 papers, 2022 to 2025). A primary or metastatic malignant neoplasm affecting the brain. "It is worth noting that the patient had a medulloblastoma, and the APC VUS is located in the gene region linked to a higher risk of brain cancer, specifically medulloblastoma." (PMID 40177144, 2025). "Of course, the expression of APC in cancer is not equivalent to playing a pathophysiologic role in cancer, and more clinical data are needed for clarification of the activity of APC in brain cancer." (PMID 35303016, 2022). "Additionally, TTI2 in prostate, APC in breast, MAD2L2 in pan-cancer, HERC2 in prostate, and MDN1 in brain cancer associated with the mutation component dMMRICA." (PMID 35764656, 2022).
chronic myeloid leukemia (5 papers, 2013 to 2024). "Using the haploid chronic myelogenous leukemia cell line HAP1, RNA sequencing (RNA‐seq) was performed to identify genes whose expression was increased by APC disruption and reversed by β‐catenin knockdown (KD)." (PMID 37096864, 2023).
Cirrhosis (5 papers, 2011 to 2025). A chronic disorder of the liver in which liver tissue becomes scarred and is partially replaced by regenerative nodules and fibrotic tissue resulting in loss of liver function. "In a methylation-specific polymerase chain reaction (PCR-MSP) analysis, APC hypermethylation was found in 61.5% of patients with HCC compared to 12.5% of patients with cirrhosis, which suggests a pathogenic role of hypermethylation in HCC." (PMID 31546948, 2019). "The antisense strand-biased methylation pattern of APC appeared in most of the non-HCC liver tissues analyzed except for cirrhosis, in which only two of six cirrhotic tissues were found to exhibit antisense strand-biased methylation by BSP sequencing." (PMID 22073196, 2011).
ductal adenocarcinoma (5 papers, 2009 to 2023).
gastric adenocarcinoma and proximal polyposis of the stomach (5 papers, 2018 to 2026). "Helicobacter pylori (H. Pylori)infection and gastric mucosal atrophy tend to be minimal when fundic gland polyposis is present, but associations with the sites of APC gene variants and family history have been understudied." (PMID 34185173, 2021). "GAPPS is caused by pathogenic germline variants in the 1B promoter region of the APC gene, with fundic gland polyposis as the presenting feature." (PMID 34185173, 2021). "For example, FAP and gastric adenocarcinoma and proximal polyposis of the stomach (GAPPS) are sometimes collectively referred to as APC-associated polyposis, while diseases that result in adenomatous polyposis, including FAP, are occasionally grouped under the term “adenomatous polyposis syndrome”." (PMID 41214301, 2026).
gastric adenoma (5 papers, 2014 to 2024). A neoplastic polyp that arises from the stomach. "First, public truncating mutations involving APC, a well-known gate-keeping gene, were observed in all of the gastric adenomas examined, suggesting that APC inactivation is the universal, initiating event in the development of gastric adenomas." (PMID 27175599, 2016). "In addition, MSI-high gastric adenomas, loss-of-functional events of APC is frequently observed, and it is considered to initiates the gastric carcinogenesis and is followed by mutations of histone modifiers and then activation of cancer-related genes." (PMID 33797633, 2021). "Biallelic, public APC inactivations were also observed for two MSI-H gastric adenomas, in that each genome contained one nonsense mutation and one out-of-frame indel involving APC (e.g., p.R215X/p.K1452fs for MSI-H1 and p.R1450X/p.Y158fs for MSI-H2, respectively)." (PMID 27175599, 2016). "Notably, all the gastric adenomas also showed biallelic APC losses with either two truncating APC mutations (e.g., out-of-frame indel and nonsense mutation) present or one truncating APC mutation present along with focal/arm-level 5p losses in the given cases." (PMID 27175599, 2016). "APC mutation data was only available for three patients with gastric adenomas, which is not enough to make any comment on a possible genotype/phenotype relationship." (PMID 24565534, 2014).
Intellectual disability (5 papers, 2016 to 2025). "Most previous case reports of patients with both FAP and intellectual disability (ID) have described deletions in all or part of chromosome 5q, including the APC locus." (PMID 39780213, 2025). "Our analysis of the deposited cases with whole-APC deletions indicated that intellectual disability is one of the major symptoms." (PMID 39632802, 2024).
invasive breast carcinoma (5 papers, 2008 to 2017). A carcinoma that infiltrates the breast parenchyma. "Of the 24 cases of invasive breast cancer with high APC methylation status by qMSP, loss of APC protein was seen in four (16.7%)." (PMID 18841156, 2008). "The collective % of alterations in CTNNB1, APC and DVL1 genes among total breast invasive carcinomas were 21% in contrast to 56% breast invasive carcinomas, PAM50 Basal-like." (PMID 27281609, 2016). "Hypermethylation of RASSF1 was most frequent, present in 14/17 cases, followed by APC in 12/17, and GSTP1 in 9/17 cases with establishment of an epigenetic monocloncal progression continuum to invasive breast cancer." (PMID 21776373, 2011). "The APC promoter region was analysed for presence or absence of methylation in formalin-fixed and paraffin-embedded tissue samples of invasive breast cancer (including 30 cases of non-IBC and 21 cases of IBC) and of non-neoplastic breast tissue from unaffected women (n=27) for control purposes." (PMID 18841156, 2008).
meningioma (5 papers, 2014 to 2024). A generally slow growing tumor attached to the dura mater. "WNT/Beta-Cantenin is another pathway associated with meningiomas with mutations of two genes linked to this pathway: APC (adenomatous polyposis coli) and E-cadherin." (PMID 25485306, 2014). "Variants typical for angiomatous (brain) meningioma are PIK3CA, KIT, PTPN11, CDH1, SMAD4, and SMARCB1; the variants typical for psammomatous meningioma are APC, FGFR2, HNF1A, STK11, and JAK3." (PMID 38476782, 2024). "Beta-catenin was upregulated and transferred to the nucleus in 71.2% of meningiomas and its nuclear localization correlated to gross deletions of APC gene (Chi square = 21,96, df = 2, p < 0.0001)." (PMID 27429002, 2016). "Taken together, APC, KDR and GSE1 mutations might contribute to meningioma growth, however, validation by Sanger sequencing and functional analyses are needed to strengthen these preliminary findings." (PMID 31470906, 2019). "Gross deletions of the APC gene were found in 47% of investigated meningiomas." (PMID 27429002, 2016). "The APC tumor suppressor is an important modulator of the WNT/Beta-Cantenin pathway and the presence of E-cadherin decreases invasiveness and recurrence of meningioma." (PMID 25485306, 2014). "Meningiomas that were harboring LOHs were also accompanied with the absence of APC protein expression or presence of mutant APC proteins (Chi square = 13.81, df = 2, p < 0.001)." (PMID 27429002, 2016). "They showed significant association between APC genetic changes and lack of wild type protein expression, or presence of mutant APC proteins in meningiomas indicating involvement of this tumour suppressor gene." (PMID 27429002, 2016). "Benign meningiomas have been shown to have deletions or other losses in the APC gene, a tumor suppressor, but these changes have not been documented in higher-grade tumors." (PMID 25485306, 2014).
metastatic colorectal cancer (5 papers, 2015 to 2025).
mucinous adenocarcinoma (5 papers, 2018 to 2025). An invasive adenocarcinoma composed of malignant glandular cells which contain intracytoplasmic mucin. "In our samples, APC was less frequently mutated in mucinous adenocarcinoma and signet-ring cell carcinoma (1 of 28; 4%) than in well, moderately, or poorly differentiated adenocarcinomas (13 of 59; 22%; p < 0.05 by Fisher’s exact test)." (PMID 29416670, 2018). "The one without concurrent KRAS mutation had a histological appearance of colloid carcinoma, with somatic ATM and APC mutation." (PMID 35180847, 2022).
oral cancer (5 papers, 2010 to 2024). "The mutational profile of APC was also investigated in oral cancer using basic research protocols." (PMID 29495520, 2018). "However, β-catenin signaling is elevated in oral cancer cells even though mutations of APC and β-catenin are rare." (PMID 20302655, 2010). "Following the example of acute myeloid leukemia, we encourage exploring the potential of APC/C as a molecular biomarker for oral cancer prognosis." (PMID 38740853, 2024). "Increased promoter methylation for APC has been reported in clinical oral cancer tissues and some data do suggest a relationship between APC methylation status and development of lymph node metastases when it is analyzed in concert with the promoter methylation status of CDH1." (PMID 22645611, 2012). "This could explain the accumulation of β-catenin in oral cancer even in the absence of a functional mutation in the APC gene (considering the fact that promoter methylation concludes with silencing of gene expression)." (PMID 29495520, 2018).
Pancreatoblastoma (5 papers, 2019 to 2024). A rare malignant epithelial neoplasm arising from the pancreas. "A missense mutation in the APC gene has also been reported in pancreatoblastoma and shown to exert reduced repression on Wnt/β-catenin signaling." (PMID 34313788, 2021). "Among them, gene mutations in the APC/β-catenin pathway were detected in pancreatoblastoma, indicating a molecular interaction between FAP and pancreatoblastoma." (PMID 30699894, 2019). "Biallelic inactivation of the APC gene has been previously identified in patients with pancreatoblastomas arising in the setting of FAP as well." (PMID 39611185, 2024).
prostate (5 papers, 2013 to 2024). "Moreover, they found an increase in PTEN loss (30% vs. 11%, q < 0.001) and Adenomatous Polyposis Coli (APC) mutations (11% vs. 5%, q = 0.001), the latter being another tumor suppressor gene implicated in prostate carcinogenesis." (PMID 38337427, 2024). "We conducted this study in the hope that through APC promoter methylation event, we can dive into a novel approach and investigate the potential of APC promoter methylation as a biomarker in bladder carcinogenesis." (PMID 39569232, 2024). "In conclusion, our findings of frequent APC and GSTP1 methylation in NTAT and their association with mortality from prostate cancer support the notion that changes in gene methylation are an early event in prostate carcinogenesis and play a role in cancer progression." (PMID 23874531, 2013). "Promoter methylation of several cancer-related genes (e.g., GSTP1, APC, RARB2, and RASSF1A) has been extensively documented in PCa and seems to occur early in prostate carcinogenesis, as demonstrated by its intermediate frequency in HGPIN lesions." (PMID 24344919, 2013).
renal carcinoma (5 papers, 2016 to 2024). A carcinoma arising from the epithelium of the renal parenchyma or the renal pelvis. "Hypermethylation on cfDNA was detected for the LRRC3B (74.1%), APC (51.9%), FHIT (55.6%), and RASSF1 (62.9%) genes in patients with renal cancer." (PMID 27725787, 2016). "The results obtained indicate that the concentration of cell-free DNA in plasma and the methylation of specific genes (such as FHIT, APC, and RASSF1) can be a significant addition to serological tumor markers in the identification of patients with renal cancer." (PMID 27725787, 2016).
seminoma (5 papers, 2013 to 2024). A radiosensitive malignant germ cell tumor found in the testis (especially undescended), and extragonadal sites (anterior mediastinum and pineal gland). "CtDNA hypermethylation at APC, GSTP1, PTGS2, p14, p16, and RASSF1A was investigated to detect seminomas and nonseminomas, with detected methylation patterns found to be similar between seminoma and nonseminomas." (PMID 38927984, 2024).
acute myeloid leukemia (4 papers, 2016 to 2024). Acute myeloid leukemia (AML) is a group of neoplasms arising from precursor cells committed to the myeloid cell-line differentiation. "Similarly, intestinal and hematopoietic stem cells carrying the truncated PPM1D allele showed increased survival after genotoxic stress and promoted APC-driven tumour growth in the intestine and the irradiation-induced acute myeloid leukaemia (AML), respectively." (PMID 39237765, 2024).